TNF (tumor necrosis factor)
Diseases named in the same sentence as TNF in open-access papers (continued):
Sharing a sentence is not in itself a finding about the gene and the disease.
infection (continued). "High levels of TNF-α, IL-6, and IFN-γ are produced from T cells responses, and they contribute to the activation of the immune system against infection." (PMID 33212789, 2020). "Infection with either NH/P68 and 22653/14 ASFV resulted in a reduced ability of moMΦ to release the same cytokines (IL-6, IL-12, TNF-α) in response to stimulation with Pam2Cys lipopeptide." (PMID 32178332, 2020). "We found obvious enhancement of TNF-α and IL-10 in both spleen and brain, indicating an inflammation status of BALB/c following EBIV infection." (PMID 33597934, 2020). "This pattern of infection was also reflected in the cytokine profiles of infected cells; IFN-α2a, IL-6, and TNF-α production was significantly enhanced 24 h after infection of M0 and M2 macrophages and was only modestly enhanced in the M1 population." (PMID 32088771, 2020). "Infection of T. gondii elicits the production of interferon gamma (IFN-γ), tumor necrosis factor (TNF), interleukin 10 (IL-10), IL-12, and several cytokine receptors, while reduces production of nitric oxide." (PMID 33330132, 2020). "Analyses of footpads, in the early phase of infection, showed that L. amazonensis infection induced the upregulation of TNF-α and TGF-β expression in both mouse strains, when compared with control groups, 24 h after infection." (PMID 32983013, 2020). "The numbers of IFN-γ+TNF-α+IL-2+ T cells were the highest among the multifunctional T cells in the Rv2882c-Rv2005c immunized mice at 12 weeks post infection, and the numbers of IFN-γ+TNF-α+ T cells were sustained until 20 weeks postinfection." (PMID 32664238, 2020). "CXCL2 (MIP‐2) and CXCL1 (KC), which are responsible for the infiltration of neutrophils and monocytes, were suppressed at the beginning of infection (6 h), whereas inhibition of CCL2 (MCP‐1), TNF‐α, IL‐6, IL‐1β and IL‐17A appeared after 24 h." (PMID 33014369, 2020). "Infection with BCG was shown to exert a detrimental effect primarily upon epithelial cells, with corresponding increases in IL8, TNFα, IL22 and IL17a cytokine release, quantified by ELISA." (PMID 33116165, 2020). "IL-1β, IL-12, and TNF levels in the TNF-/- mice showed significant decreases compared with those of the controls TNFf/f and BTNF-/- mice at 3 weeks after infection." (PMID 32742607, 2020). "Transcriptional levels of IFN-α, TNF-α, IL-12, IL-6, and IFN-α were upregulated, while RANTES was downregulated following factor H treatment for the H1N1 subtype at 6 h post-infection." (PMID 33488586, 2020). "One-week post infection, infected ECD mice had significantly higher levels of the proinflammatory cytokine TNF-α compared to uninfected ECD, infected and uninfected control mice (p < 0.001)." (PMID 32958779, 2020). "Analysis of serum IL-6 and TNFα concentrations in PBS treated animals at day 0, day 8 and day 12 post-infection showed that concentrations of both cytokines increased marginally but not significantly overall by day 8 post challenge." (PMID 32584899, 2020). "A549 cells infected with HEV1–Sar55 produce proinflammatory cytokines/chemokines, including IL-6, TNF-α, and RANTES as early as 12 h post-infection." (PMID 32731452, 2020). "The levels of inflammatory markers such as TNF-α, IL-6, and MCP-1, is all correlated with the severity of infection." (PMID 32434424, 2020). "In this model we observed a significant increase in total neutrophils in Peli1−/− animals at 72 h post-instillation, and again saw higher levels of IL-6 and TNFα in BAL fluid at both 72 and 96 h post-infection." (PMID 32984077, 2020). "Studies using spiramycin-loaded chitosan nanoparticles on mice treated with RH for 7 days after infection showed an increase in cytokines such as INF-γ, (TNF-α), and an increase in IgM against parasitoid tachyzoites." (PMID 33163635, 2020).
infection (continued). "Simultaneously, the knockdown of FcγRI or FcγRIII in porcine AMs during PRRSV-ADE infection significantly upregulated the production of IFN-α and TNF-α, while it significantly downregulated the production of IL-10." (PMID 32046249, 2020). "During infection, PCT can be produced by several cell types and many organs in response to pro-inflammatory cytokines (e.g., tumor necrosis factor-α and interleukin-6)." (PMID 32160878, 2020). "Studies using isolated feline alveolar macrophages and/or monocytes have shown increases in G-CSF, GM-CSF, TNF-α and VEGF production at 2–3 days post infection with FIPV." (PMID 33121170, 2020). "Third, markers of inflammation, including neutrophil infiltration and the production of proinflammatory cytokines, such as TNF-α, IL-1β and IL-6, production in the BALF were determined 24 h post-infection." (PMID 32197534, 2020). "After infection for 12 h to 24 h, the expressions of IFN-α, IFN-β, TNF-α, IL-6, IL-8, and IL-12 began to increase continuously, and the levels of transcriptions of these inflammatory factors peaked at 24 h." (PMID 32133381, 2020). "TNF-α engagement of its receptors, TNF-R1 and TNF-R2, mediates cell recruitment to sites of infection, immune cell activation, and production of antimicrobial molecules, cytokines, and can result in programmed cell death." (PMID 33520735, 2020). "A significant reduction in the systemic TNF-α levels (p < 0.05) was found in animals that received either IFN-λ pre- and post-infection (Group 2), or IFN-λ pre- and IFN-α post-infection (Group 5)." (PMID 32118067, 2020). "Virus-specific CD4+ T cells detected at 2 years after infection in recovered individuals exhibited central memory while CD8+ T cells effector memory phenotypes, and CD8+ T cells produced high levels of IFN-γ and TNF-α upon peptide stimulation." (PMID 33062077, 2020). "In contrast, infection with MCMV down-regulated the expression of IL-10 and increased production of inflammatory cytokines IL-6 and TNFα." (PMID 32455939, 2020). "Conversely, expression of IE1dl410-420 led to a marked increase in infection-related induction of the IFNB1, IFNL1, CCL5, TNF and PML genes." (PMID 32365141, 2020). "IAV-induced transcriptional levels of IFN-α, TNF-α, IL-12, IL-6, IFN-α, and RANTES were reduced following factor H treatment for the H1N1 subtype at 6 h post-infection." (PMID 32269562, 2020). "There, type I/III interferons, tumor necrosis factor alpha (TNF-α-) interleukin-1 (IL-1), IL-6, and IL-18, among other components of the innate immunity, control the infection in the majority of the individuals." (PMID 33117371, 2020). "Macrophages infected with L. amazonensis, even in the presence of IFN-γ and TNF-α, fail to eliminate the parasites altogether due to the formation of the parasitic vacuole, which may compromise the leishmanicidal action of NO and ROS, favoring the maintenance of the infection." (PMID 32908533, 2020). "Infection with P. zopfii GT-II in MEC induced early IL-1β, TNF-α and Cxcl-1 gene expression (after 2 hpi)." (PMID 31959834, 2020). "Although TNF-α, IL-6, and IFN-γ were reduced by 5 weeks post-infection, they were still significantly elevated relative to uninfected controls (white background)." (PMID 32973293, 2020). "The infection of human AMs by the RSV stimulates the secretion of several proinflammatory cytokines, including IL-6, TNF-α, IL-1β, and IL-8." (PMID 32660087, 2020). "In order to improve our knowledge of the interaction between the immune system and S. haemolyticus during the infection, we investigated the expression of IL1β, IL4, IL17, IFNγ, TNFα, TGFβ and IL10 by PBMCs infected withS." (PMID 32799619, 2020). "Ultimately, the upregulation of effector molecules, such as cytokine TNF, cytolytic molecule perforin (PRF1), and adhesion molecule ICAM1, enhance the protection against infection, killing of bacterial-infected cells, and cell migration to infected tissues." (PMID 32582206, 2020).
infection (continued). "We subsequently analyzed the kinetics of the most intensive pro-inflammatory cytokines including TNF-α, IL-1β, IL-6, and IL-18 in sera of pigs upon SY18 infection." (PMID 33553280, 2020). "Yet, between 38–48 days post infection, all tested pro-inflammatory cytokines (IFN-γ, TNF, IL-6 and MIF) increased or remained high in TgAlbCre-IL10-/- mice, but not in the other strains." (PMID 32012211, 2020). "The results showed that the gene expression of TNF-α and IFN-γ was significantly increased following H9N2 AIV infection (P < 0.01)." (PMID 33193136, 2020). "It is well known that IL-22 producing CD4+ T cells are essential for controlling Cr infection; however, the T cell-derived cytokines (IL17A, IFN-γ and TNF-α) contribute to intestinal tissue injury either directly or indirectly." (PMID 33076301, 2020). "Mice treated with antibodies against IL-1β and TNF-α, or with inhibitor of inducible NO synthase (iNOS), showed a reduced incidence of VID upon infection with a low dose of EMCV-D." (PMID 32727064, 2020). "Similar results were found in murine models infected with Plasmodium falciparum or coinfected with Toxocara canis and Toxoplasma gondii that induced an increase in TNFα, IFNγ, IL10 and IL4 brain production following infection with these parasites." (PMID 33322180, 2020). "The spleen analysis showed a significant enhancement of proinflammatory cytokines expression – TNF-α, IFN-γ, and IL-12 – and regulatory cytokine – TGF-β – on the first day after infection in C3H/He mice, in comparison with C57BL/10." (PMID 32983013, 2020). "Serum TNF-α levels in the PBS-immunized group and the OPSBa- and OPSBa+Al-immunized groups increased markedly following infection." (PMID 32244903, 2020). "To further ascertain the molecular response during the infection of C. sinensis, we measured the CD4+T cell subsets-related cytokines, including IL-10, IL-17, IL-4, IL-2, and TNF-α by ELISA methods." (PMID 33489026, 2020). "At 1 week post-infection, when T. gondii infection is systemic, mice had elevated circulating IFN-γ, IL-1β, IL-6, and TNF-α compared to uninfected controls (grey background)." (PMID 32973293, 2020). "IFN-β, TNF-α, IL-6, and IL-12p40 were significantly upregulated in response to DIP infection compared to WT." (PMID 33298958, 2020). "Ag-expCD4+ T cell effector function continued to deteriorate between days 9 and 15 of infection, with cells on day 15 of infection, expressing low levels of Ki67, ICOS, and CD25 and producing very low levels of TNF, IFN-γ, IL-2, and IL-10." (PMID 32817333, 2020). "An interesting finding was that some mediators were more affected by TLR2 loss in the brain compared to the galea, including IL-1β, CCL2, TNF-α, IL-6, and CXCL2, which was particularly evident at day 14 post-infection." (PMID 32290861, 2020). "On the 45th day of infection, infected diabetic mice presented higher IFN-γ levels, a higher tumor necrosis factor (TNF)-α:IL-10 ratio, and lower adhesion molecule expression levels than nondiabetic mice." (PMID 33312173, 2020). "We found that overexpression of TRIM35 in THP-1 cells significantly enhanced transcription of IFNB1, TNFα, IL6, and ISG56 after infection with SeV." (PMID 32562145, 2020). "These Th17 cytokines can recruit neutrophils and monocytes to the site of infection or inflammation and lead to the activation of other downstream cytokine and chemokine cascades, such as IL1, IL6, TNF-α, TGF-β, IL8, and MCP-1." (PMID 31089478, 2019). "In the CNS of WT mice, increased IFN-α1, IFN-β, TNF, IL-1α, IL-1β, IL-6, and IFN-γ mRNA levels were seen at day 4 post infection, and with the exception of IFN-α1, which decreased slightly, cytokine mRNA levels increased further by day 6 post infection." (PMID 31511023, 2019). "As expected, several cytokines including TNF-α, IL-1β, IL-6, IL-8, and IFN-γ were significantly increased in a time-dependent manner upon virulent Mtb strain H37Rv infection detected by qRT-PCR in hMDMs." (PMID 30717477, 2019).
infection (continued). "At 4 days after the infection with DENV, blood level of IL-1β and TNF-α mRNA and protein was increased in DENV2-infected mice and DENV2-infected mice treated with IL-1RA but not in mock-infected mice." (PMID 31824450, 2019). "A single unilateral injection of EcoHIV (1 × 106 pg) directly into the caudate putamen resulted in a significant increase in inflammatory markers (TNFα, IL-1β, IFNγ, CCL2, CCL3, CXCL10) 5 days after infection." (PMID 31263138, 2019). "In contrast, after infection, the F3 vaccine induced the strongest IFN-γ and TNF-α secretion, while the chimera, followed by the F3 and NH36 vaccines, was still predominant for the production of IL-10." (PMID 31024556, 2019). "TNF responses in hMoDC were only observed with USUV at 24 h, and at 48 h after infection with the closely related viruses of the JEV serocomplex (JEV, WNV, and USUV)." (PMID 30746342, 2019). "Univariate analysis for these variables confirmed a significant positive correlation between the acquisition of infection and pre-challenge ADCVI activity, Env-specific TNF-α+ CD4 T cells or Env-specific IFN-γ+ TNF-α+ cells." (PMID 30778066, 2019). "In this paper we showed that macrophages lacking lincRNA-EPS exhibit increased expression of inflammatory cytokines such as TNF-α, IL-6, IL1-β, and CCL5 upon infection with L. monocytogenes." (PMID 32039056, 2019). "After the infection with DENV2, all E-derived peptides induced a TNF-α response in CD4+ and CD8+ T cells collected from pE1D2-vaccinated animals, except for CD8+ T lymphocytes stimulated with the peptide E98." (PMID 31333657, 2019). "It is known that the proinflammatory cytokine response (such as TNF-α and IL6 production) against any infection has several drawbacks in the host, such as pathological damage to tissues." (PMID 31089478, 2019). "Several differentially expressed genes identified in our study (i.e., ADIPOQ, CCL3) are related to tumor necrosis factor (TNF), a cytokine that produces an immune response to help prevent the spread of infection." (PMID 31788200, 2019). "Defensin 1 administration to macrophages 1 h and 5 h after infection with D39 (MOI10) led to a reduction of bacteria-induced release of key inflammatory cytokines such as IL-1β, IL-6, and TNF-α." (PMID 31657264, 2019). "A strong T-cell response is induced after DENV natural infection, exhibiting an effector memory phenotype, IFN-γ and TNF-α production, and cytotoxic potential." (PMID 30678246, 2019). "Consistent with increased cellular recruitment, evaluation of lung homogenates showed an overall increase in TNF, IL-1β, IL-6, IL-17 and KC (CXCL1) in Mtb-LT infected mice at four weeks following infection compared with Mtb-HT infected mice." (PMID 30840702, 2019). "FasL and TNFα remained undetectable, while the TNF-related apoptosis-inducing ligand (TRAIL) seemed to be the most abundant one before infection." (PMID 30862035, 2019). "We examined the effect of α-mangostin against dengue virus (DENV) infection in human peripheral blood mononuclear cells (PBMC) by the measurement of virus titer and TNF-α and IFN-γ cytokines concentration post infection." (PMID 31538308, 2019). "Both TNFα and IL-6 mRNA were markedly upregulated upon AB14 (H5N1) infection and remained at these elevated levels." (PMID 30813415, 2019). "In neuronal cultures, infection with HSV-1 upregulated IFN-alpha, TNF-alpha, CXCL9, and CXCL10, while addition of NO downregulated all tested cytokines and chemokines." (PMID 30886672, 2019). "Remarkably, the frequency of CD3+TCRαβ+ myeloid cells was similar in tmTNF KI vs. WT mice and TNF KO, implying that tmTNF is enough to recover the ability to maintain CD3+TCRαβ+ myeloid cells at the infection site." (PMID 31787969, 2019).
infection (continued). "Lower levels of IL-8 and TNF-α in the ΔrfaL group may correspond to the protective chemoattraction of neutrophils to the inflammatory site as a mechanism of protection by rough Salmonella enterica strains against subsequent infection with virulent Salmonella Typhimurium." (PMID 31540295, 2019). "Using an in vitro model of BCG infection, the authors confirmed that the infection increased the frequency of CD3+ macrophages, and the presence of TNF was essential to maintain this cell subpopulation." (PMID 31787969, 2019). "At 24 h post-infection, the ESRD group showed significantly lower levels of IL-1Ra, IL-6, IL-8, IL-10, IL-12p40, TNF-α, VEGF, MCP-1, and MIP-1b as compared to the control group." (PMID 31875015, 2019). "During infection (days 4–11), six cytokines and chemokines (IP-10, MIP-1α, IL-23, GM-CSF, TNF-α and TNF-α: IL-10 ratio) differed significantly between rhesus who suffered SMA and cynomolgus who did not." (PMID 31831787, 2019). "Our results show that infection with this protozoan influences the peripheral and placental immune response and that it is mediated by a mixed of Th1 (IFN-γ and TNF-α), Th2 (IL4) and Treg (IL10) cytokines." (PMID 31533826, 2019). "A significant decrease in TNF-α-induced NF-κB-mediated luciferase activity was observed between 8 and 12 h post-SVA infection." (PMID 30918505, 2019). "Further, TcG2/TcG4-vaccinated mice exhibited potent expansion of poly-functional CD8+T cells with TNF-α/IFN-γ production and cytolytic phenotype post-infection." (PMID 31293599, 2019). "We extended our analysis beyond the conventional IFNγ response by measuring TNFα, IL2, and IL17a producing T-cells as well, both in the periphery as well as at the site of the infection at various time points after infection." (PMID 31736945, 2019). "In summary, for the first time it has been shown that CHIKV triggers robust TNF production in the host macrophages via both p-p38 and p-JNK/p-c-jun pathways and the interaction of viral protein, nsP2 with these MAPKs during infection." (PMID 31031770, 2019). "In general, both the pro-inflammatory cytokines (TNF-α and MCP1) and the anti-inflammatory cytokines IL-6 and IL-10 increased 1 hour of infection in the XID infect APerC." (PMID 31536488, 2019). "During the course of an acute LCMV WE infection, CD8 T cells expanded 2-fold more in NCR1gfp/gfp compared to WT mice, including virus-specific TNF and IFNγ-producing CD8 T cells." (PMID 30995287, 2019). "IAV infection increased the mRNA expression at day 3 post-infection (105 PFUs) of IL-6, CCL3, CXCL2, and G-CSF, IL-1β and TNF-α (p < 0.05)." (PMID 30787331, 2019). "In order to explain the reduced SF162 (R5) infection in Th2 cell cultures induced by SEA exposed DCs we characterized the cytokine/chemokine (IFN-γ, IL-4, IL-2, TNF-α, MIP-1β) expression profiles of the different Th cell populations." (PMID 31487324, 2019). "Our results reveal that infection with L. braziliensis increases the expression of TLR2 and TLR4 on inflammatory monocyte subsets and this increase is accomplished mainly by TNF production." (PMID 31119102, 2019). "PVSRIPO activation of DCs comes in part by a sublethal infection producing low viral progeny and is exaggerated when exposed to tumour lysate, as measured by CD40, CD80, IFN-β and TNF-α expression." (PMID 31100962, 2019). "The proinflammatory cytokines TNF-α, IFN-γ, IL-1β, IL-2, IL-5, and IL-6 also showed high levels of expression during the infection period, suggesting that the balance between cytokines determines the course of infection." (PMID 31636507, 2019). "Serum concentrations of IFN-γ and IL-6 followed the same profile observed for TNF-α concentration, and MCP-1 levels were detected only on the third day after infection." (PMID 31687410, 2019).